CAMLG (calcium modulating ligand)
Description:
Required for the post-translational delivery of tail-anchored (TA) proteins to the endoplasmic reticulum. Together with GET1/WRB, acts as a membrane receptor for soluble GET3/TRC40, which recognizes and selectively binds the transmembrane domain of TA proteins in the cytosol. Required for the stability of GET1. Stimulates calcium signaling in T cells through its involvement in elevation of intracellular calcium. Essential for the survival of peripheral follicular B cells (By similarity).
Synonyms: CAML; GET2; CDG2Z
Tractability: Antibody: UniProt predicts a signal peptide or a membrane-spanning region. PROTAC: ubiquitination databases record sites on it; its protein half-life has been measured.
Gene: Protein-coding gene on chromosome 5 (134,737,608 to 134,752,705, forward strand). Ensembl gene ENSG00000164615.
Subcellular location: Endoplasmic reticulum membrane
Subcellular location (Human Protein Atlas): Vesicles; Nucleoli; Nucleoplasm
Pathways (Reactome):
Protein localization: Insertion of tail-anchored proteins into the endoplasmic reticulum membrane
Gene Ontology:
Molecular function: protein binding; ubiquitin protein ligase binding
Biological process: negative regulation of proteasomal ubiquitin-dependent protein catabolic process; negative regulation of protein ubiquitination; protein stabilization; tail-anchored membrane protein insertion into ER membrane; B cell homeostasis; defense response; protein insertion into ER membrane; signal transduction
Cellular component: cytoplasm; endoplasmic reticulum; endoplasmic reticulum membrane; GET complex; membrane
Genetic constraint (gnomAD): Loss-of-function variants: 17 observed, 20.78 expected, observed/expected ratio (o/e) 0.82, 90% interval 0.56 to 1.23. The upper end of that interval is the gene's LOEUF score, 1.23, which puts it in group 5 of 6, group 1 being the genes least tolerant of losing a copy. Missense variants: 331 observed, 354.78 expected, observed/expected ratio (o/e) 0.93, 90% interval 0.85 to 1.02. Synonymous variants: 130 observed, 144.24 expected, observed/expected ratio (o/e) 0.9, 90% interval 0.78 to 1.04.
Gene-disease validity (ClinGen):
ClinGen rates the evidence that CAMLG causes each of these diseases.
congenital disorder of glycosylation, type IIz (autosomal recessive): Limited.
Homologues: Orthologues: chimpanzee CAMLG (99% identical), macaque CAMLG (99% identical), dog CAMLG (94% identical), pig CAMLG (91% identical), guinea pig CAMLG (89% identical), mouse Caml (89% identical), rabbit CAMLG (85% identical), rat Camlg (64% identical), tropical clawed frog camlg (57% identical), zebrafish camlg (46% identical).
Diseases named in the same sentence as CAMLG in open-access papers:
CAMLG is named in the same sentence as 29 diseases in open-access papers, as found by Europe PMC text mining. Sharing a sentence is not in itself a finding about the gene and the disease. The quoted sentences say what the papers report.
breast carcinoma (3 papers, 2018 to 2024). "It has been also shown that CAMLG is involved in the intracellular calcium increased mobilization, which activates signal transduction and activation required for the prolactine-dependent growth of breast cancer cells." (PMID 30154321, 2018).
cholangiocarcinoma (2 papers, 2021 to 2022). A carcinoma that arises from the intrahepatic biliary tree (intrahepatic cholangiocarcinoma) or from the junction, or adjacent to the junction, of the right and left hepatic ducts (hilar cholangiocarcinoma). "Circ-CCAC1 (Cholangiocarcinoma-associated circular RNA 1) facilitated CCA growth and migration via sponging miR-514a-5p to elevate the expression of YY1 (Yin Yang 1) and CAMLG (calcium modulating ligand)." (PMID 35255950, 2022).
disorder of glycosylation (2 papers, 2022 to 2025). A disease that has its basis in the disruption of glycosylation. "As well as glycosylation disorders, it is also important that CAMLG-CDG and other disorders of the TRC pathway are viewed within the context of the wider roles of TA proteins." (PMID 35262690, 2022).
myeloma (2 papers, 2023 to 2024). "Furthermore, the employment of CAR-T cells targeting the transmembrane activator and calcium modulating ligand (CAML) interactor (TACI) offer a dual benefit since TACI is not only a myeloma target but is also expressed by Tregs." (PMID 39594822, 2024).
congenital myasthenic syndrome (1 paper, 2023). Congenital myasthenic syndrome (CMS) is a group of genetic disorders of impaired neuromuscular transmission at the motor endplate characterized by fatigable muscle weakness. "Some examples of other (including multiple) glycosylation pathway defects discovered in the last five years are ATP6VI1-, GO7- (Congenital myasthenic syndrome), GET4-, GFUS- and GNPNAT1-CDG, and most recently CAMLG-CDG." (PMID 37858231, 2023).
epilepsy (1 paper, 2022). A brain disorder characterized by episodes of abnormally increased neuronal discharge resulting in transient episodes of sensory or motor neurological dysfunction, or psychic dysfunction. "Mutations in ASNA1 are associated with pediatric cardiomyopathy and mutations in its pathway protein calcium modulating ligand (CAML) are linked in patients to hypotonia, brain abnormalities, and epilepsy." (PMID 36480541, 2022).
viral infections (1 paper, 2018). "In addition, CAMLG has been demonstrated to be involved in modulation of apoptosis during viral infections." (PMID 30154321, 2018).
genetic disorder (1 paper, 2022). "We report the third identified patient with a genetic disorder caused by disruption of the TRC pathway and the first caused by a pathogenic variant in CAMLG, encoding CAML." (PMID 35262690, 2022).
CAMLG also shares sentences with these, for which no sentence is quoted: cancer (5 papers); melanoma (3); tumor (3); congenital disorder of glycosylation (2); Allergy (1); asthma (1); autoimmune disease (1); B-cell lymphomas (1); breast tumors (1); common variable immunodeficiency (1); depression (1); infection (1); lymphoblastic lymphoma (1); lymphoma (1); motor neuron disease (1); movement disorder (1); neurological disorder (1); neutropenia (1); non-small cell lung carcinoma (1); polycystic liver disease (1); tubulointerstitial kidney disease (1).